WARS1 (tryptophanyl-tRNA synthetase 1)
Description:
Catalyzes the attachment of tryptophan to tRNA(Trp) in a two-step reaction: tryptophan is first activated by ATP to form Trp-AMP and then transferred to the acceptor end of the tRNA(Trp). [Isoform 1]: Has no angiostatic activity. [T2-TrpRS]: Possesses an angiostatic activity but has no aminoacylation activity. Inhibits fluid shear stress-activated responses of endothelial cells. Regulates ERK, Akt, and eNOS activation pathways that are associated with angiogenesis, cytoskeletal reorganization and shear stress-responsive gene expression. [Isoform 2]: Has an angiostatic activity.
Synonyms: IFP53; IFI53; WARS; GAMMA-2; HMN9; HMND9; NEDMSBA
Tractability: Small molecule: a structure with a bound ligand is known; it has a high-quality binding pocket. PROTAC: ubiquitination databases record sites on it.
Target class: Enzyme; Ligase
Gene: Protein-coding gene on chromosome 14 (100,333,784 to 100,376,805, reverse strand). Ensembl gene ENSG00000140105.
Subcellular location: Cytoplasm
Subcellular location (Human Protein Atlas): Cytosol
Pathways (Reactome):
Metabolism of proteins: Cytosolic tRNA aminoacylation
Gene Ontology:
Molecular function: protein binding; protein domain specific binding; protein homodimerization activity; protein kinase binding; protein-macromolecule adaptor activity; tryptophan-tRNA ligase activity; aminoacyl-tRNA ligase activity; ATP binding; nucleotide binding
Biological process: intracellular signal transduction; regulation of angiogenesis; negative regulation of cell population proliferation; translation; tryptophanyl-tRNA aminoacylation; tRNA aminoacylation for protein translation
Cellular component: cytosol; extracellular exosome; nucleus; protein-containing complex; cytoplasm
Genetic constraint (gnomAD): Loss-of-function variants: 13 observed, 45.36 expected, observed/expected ratio (o/e) 0.29, 90% interval 0.19 to 0.46. The upper end of that interval is the gene's LOEUF score, 0.46, which puts it in group 2 of 6, group 1 being the genes least tolerant of losing a copy. Missense variants: 431 observed, 621.64 expected, observed/expected ratio (o/e) 0.69, 90% interval 0.64 to 0.75. Synonymous variants: 206 observed, 233.18 expected, observed/expected ratio (o/e) 0.88, 90% interval 0.79 to 0.99.
Gene-disease validity (ClinGen):
ClinGen rates the evidence that WARS1 causes each of these diseases.
distal hereditary motor neuropathy (autosomal dominant): Limited.
Homologues: Orthologues: chimpanzee WARS1 (100% identical), macaque WARS1 (97% identical), dog WARS1 (94% identical), pig WARS1 (93% identical), mouse Wars1 (90% identical), rat Wars1 (89% identical), guinea pig WARS1 (88% identical), tropical clawed frog wars1 (77% identical), rabbit WARS1 (75% identical), Drosophila melanogaster TrpRS (56% identical), Caenorhabditis elegans wars-1 (53% identical), zebrafish wars1 (45% identical), and 1 more. Paralogues in human: WARS2 (14% identical).
Diseases named in the same sentence as WARS1 in open-access papers:
WARS1 is named in the same sentence as 61 diseases in open-access papers, as found by Europe PMC text mining. Sharing a sentence is not in itself a finding about the gene and the disease. The quoted sentences say what the papers report.
colorectal cancer (5 papers, 2015 to 2023). A primary or metastatic malignant neoplasm that affects the colon or rectum. "A similar effect of Gas1 transfection was observed in the expression of Wars1, a gene whose low expression has been correlated with poor prognostic in colorectal cancer patients." (PMID 26161998, 2015). "In contrast to LARS1, IHC using tissue microarrays of colorectal cancer revealed a negative correlation between WARS1 protein level and recurrence risk, lymph node metastasis and a more advanced stage, suggesting the prognostic value of the WARS1 protein level." (PMID 35501376, 2022). "Predominant deletions and mutations in WARS1 feature at the DNA level for many cancer types, including SKCM, cholangiocarcinoma (CHOL), BLCA, cervical squamous cell carcinoma, endocervical adenocarcinoma (CESC), esophageal carcinoma (ESCA), and colorectal cancers." (PMID 33266490, 2020).
viral infection (5 papers, 2015 to 2023). "Moreover, the Tryptophanyl-tRNA Synthetase encoding WARS1, which stimulates immunity against viral infection, chemokines CXCL11, CCL4 and CCL4 receptor CCR5 were also significantly downregulated in low viral load positive old samples compared to age matched control." (PMID 32511341, 2020).
ovarian carcinoma (4 papers, 2021 to 2024). A malignant neoplasm originating from the surface ovarian epithelium. "Afterward, univariate Cox regression analysis was performed to evaluate the prognostic value of each tryptophan metabolism-related gene in the TCGA ovarian cancer cohort, with IDO1, ALDH3A2, HADHA, OGDHL associated with risk values, and CAT, WARS1 involved in protective factors." (PMID 38468343, 2024).
Charcot-Marie-Tooth disease (3 papers, 2023 to 2025). An inherited degenerative disorder involving the peripheral nerves. "WARS1 has been implicated in autosomal dominant distal hereditary neuropathy and Charcot-Marie-Tooth disease." (PMID 41191133, 2025). "The most common condition, the Charcot-Marie-Tooth disease (CMT), is associated with dominant, monoallelic mutations in six aaRSs genes (e.g.,YARS1, MARS1, KARS1, WARS1, AARS1, GARS1, and HARS1)." (PMID 37495112, 2023). "Thus far, autosomal dominant mutations in AARS1, GARS1, HARS1, MARS1, WARS1, SARS1 and YARS1 have been linked to peripheral neuropathies, predominantly Charcot-Marie-Tooth (CMT) disease." (PMID 37274211, 2023).
COVID-19 (3 papers, 2023 to 2025). A disease caused by infection with severe acute respiratory syndrome coronavirus 2. "We uncovered gene-regulatory mechanisms at disease loci with therapeutic implications, such as WARS1 in hypertension, IL7R in dermatitis and IFNAR2 in COVID-19." (PMID 40038547, 2025).
Sepsis (3 papers, 2020 to 2024). Sepsis is defined as life-threatening organ dysfunction caused by a dysregulated host response to infection. "Highly elevated WARS1 levels can be used to stratify patients with sepsis and septic animals associated with hyperinflammation and early mortality." (PMID 38177528, 2024). "WARS1 substantially upregulates a cluster of genes associated with hyperinflammatory sepsis, and rWARS1 injection accelerates hypercytokinemic septic death in mice." (PMID 38177528, 2024). "Tryptophanyl-tRNA synthetase 1 may represent a theranostic target for identifying patients with sepsis who are at risk of hyperinflammatory mortality and help control inflammation." (PMID 38177528, 2024). "Our investigation revealed that excessive secretion of WARS1 represents a potential therapeutic target in severe hypercytokinemic sepsis." (PMID 38177528, 2024). "Taken together, these data suggest that WARS1 is an upstream exacerbating factor and can be used as a therapeutic target for severe sepsis with hypercytokinemia." (PMID 38177528, 2024). "Following CS inoculation, plasma WARS1 levels continuously increased and were significantly higher according to severity, suggesting its potential as a severity biomarker for sepsis." (PMID 38177528, 2024). "To further examine the correlation of plasma WARS1 levels with the severity of septic mice, we used mice with moderate sepsis (CS18mg), whose mortality rate is similar to that of the human cohort." (PMID 38177528, 2024). "To evaluate the therapeutic feasibility of targeting WARS1 in sepsis, we tested the effects of the anti-WARS1 MAb on severely ill, septic mice." (PMID 38177528, 2024). "Consistent with our experimental findings, in clinical settings, we found WARS1 to be greatly secreted into the blood of patients with sepsis more than in those with sterile inflammatory disorder." (PMID 32899943, 2020). "WARS1 has also been reported to be a biomarker for predicting death in sepsis." (PMID 38177528, 2024). "To investigate how WARS1 is involved in sepsis pathogenesis and progression, we first performed an RNA-sequencing (RNA-seq) analysis of human peripheral blood mononuclear cells (hPBMCs) treated with recombinant human full-length WARS1 (hFL-WARS1, 50 nM)." (PMID 38177528, 2024). "High plasma WARS1 levels stratified the early death of critically ill patients with sepsis, along with elevated levels of cytokines, chemokines, and lactate, as well as increased numbers of absolute neutrophils and monocytes, and higher Sequential Organ Failure Assessment (SOFA) scores." (PMID 38177528, 2024). "Taken together, these results suggest that WARS1 neutralization and its combination with antibiotics protects severely ill septic mice from lethality by dampening excessive cytokine and chemokine productions and organ destruction in severe sepsis." (PMID 38177528, 2024). "Further, we highlight the application of WARS1-neutralizing monoclonal antibody, simultaneously suppressing multiple proinflammatory cytokines and chemokines, as a promising therapy for preventing death in systemic severe hyperinflammatory sepsis." (PMID 38177528, 2024). "Since the data suggested that WARS1 is an upstream aggravating factor for hyperinflammatory sepsis, we tested whether WARS1 indeed worsens sepsis in vivo." (PMID 38177528, 2024). "In this study, we investigated how WARS1 might be used as a theranostic target for severe sepsis with hypercytokinemia." (PMID 38177528, 2024). "A potential theranostic approach involving blood-circulating WARS1-guided patient stratification and targeted therapy using anti-WARS1 MAb may help improve the management of critically ill patients with sepsis through a precision medicine strategy." (PMID 38177528, 2024). "Patients with sepsis have been found to have high levels of WARS1 in their blood." (PMID 38177528, 2024). "Collectively, WARS1-mediated TREM-1 could be an attractive target for sepsis treatment owing to its ability to modulate innate immune responses." (PMID 32899943, 2020).
Sepsis (continued). "Collectively, secreted WARS1 may represent an expected sepsis drug target at the apex of the TLRs/TREM-1 signaling cascade." (PMID 32899943, 2020). "Further, since vertebrate WARS1 shares a high degree of similarity in its amino acid sequence, other models, such as the minipig or nonhuman primate sepsis model, could probably be used to simulate human sepsis clinical conditions more accurately." (PMID 38177528, 2024). "Finally, WARS1 neutralization could improve survival and, in conjunction with antibiotics, almost completely save the lives of mice from severe sepsis." (PMID 38177528, 2024). "The objective of this study was to explore the potential of WARS1 as a theranostic target for hypercytokinemic severe sepsis by examining an ICU sepsis cohort, sepsis animal models, and in vitro RNA-seq." (PMID 38177528, 2024). "Secreted human tryptophanyl-tRNA synthetase 1 (WARS1), an endogenous ligand for Toll-like receptor (TLR) 2 and TLR4 against infection, activates the genes that signify the hyperinflammatory sepsis phenotype." (PMID 38177528, 2024). "Nonetheless, considering the pathological complexity of sepsis, we do not think that measuring a specific WARS1 level at a given point would work as a sole determinant to stratify the patients who would respond to the anti-WARS1 MAb treatment." (PMID 38177528, 2024).
cutaneous melanoma (2 papers, 2024 to 2025). A primary melanoma arising from atypical melanocytes in the skin. "Increased WARS1 gene expression has been linked with improved prognosis in cutaneous melanoma and colon adenocarcinoma." (PMID 41225774, 2025).
neuropathy (2 papers, 2022 to 2023). A disorder affecting the nervous system that manifests with pain, tingling, numbness, and/or muscle weakness. "It is also possible that neuropathy associated WARS1 variants cause additional aberrant protein interactions, which may disrupt other cellular processes." (PMID 37274211, 2023).
age-related macular degeneration (1 paper, 2024). Age-related loss of vision in the central portion of the retina (macula), secondary to retinal degeneration. "Five of these proteins (protein-coding genes ECI1, LCT, and NPTXR for glaucoma, WARS1 for age-related macular degeneration (AMD), and SIGLEC14 for diabetic retinopathy (DR)) are newly reported." (PMID 39408566, 2024).
endotoxemia (1 paper, 2024). "We created an anti-human WARS1-neutralizing antibody that suppresses proinflammatory cytokine expression in marmosets with endotoxemia." (PMID 38177528, 2024).
glaucoma (1 paper, 2024). Increased pressure in the eyeball due to obstruction of the outflow of aqueous humor. "A total of 11 unique protein-coding genes posterior probability (PP) of H4 > 0.70 finally remained, including GSTM3 for senile cataract, WARS1, C3, IGFBP7, and PILRA for AMD, ECI1, LCT, and NPTXR for glaucoma, EFEMP1 for myopia, and SIRPG and SIGLEC14 for DR." (PMID 39408566, 2024).
Hypertension (1 paper, 2025). The presence of chronic increased pressure in the systemic arterial system. "The alternative allele of rs724391 (C) is associated with decreased excision of exon 10, higher plasma protein levels of WARS1 and increased risk of hypertension." (PMID 40038547, 2025). "Here we found a cis-sQTL for excision of exon 10 of WARS1 (encoding a portion of the tRNA synthetase protein domain), which colocalized with both the WARS1 pQTLs and risk for hypertension in FinnGen." (PMID 40038547, 2025).
intellectual disabilities (1 paper, 2024). "Mutations of the tryptophanyl-tRNA Synthetase 1 (WARS1) have been associated with various human diseases, ranging from intellectual disabilities to cancer and metastasis." (PMID 38575580, 2024). "More recently, mutations in the tryptophanyl-tRNA synthetase 1 (WARS1) have been linked to various human diseases, from intellectual disability to various types of cancer." (PMID 38575580, 2024).
myopia (1 paper, 2024). "Eight pairs (protein-coding genes TOM1L2, MXRA7, RHPN2, and HINT1 for senile cataract, WARS1 and TDRD7 for AMD, STAT6 for myopia, and TPPP3 for DR) are newly reported in this study." (PMID 39408566, 2024).
cancer (21 papers, 2019 to 2025). A tumor composed of atypical neoplastic, often pleomorphic cells that invade other tissues. "Mutations in multiple domains of WARS1 have been identified in other cancer types, including cervical squamous carcinoma, colorectal cancer, and cutaneous melanoma." (PMID 41350269, 2025). "In humans, WARS1 expression is induced by interferon γ and it is implicated in multiple physiopathological processes such as immunity or cancer." (PMID 38651369, 2024). "For example, WARS1 is associated with the progression and prognosis of solid tumors, designating it as a promising cancer marker and a therapeutic candidate." (PMID 36675119, 2023). "In parallel, pathway enrichment showed that WARS1 expression was related to enhanced immune-cell infiltration, activation of the cancer immunity cycle, and upregulation of cell-cycle and DNA-repair pathways, together with stromal programs including EMT and angiogenesis." (PMID 41145546, 2025). "However, at the RNA level, WARS1 is mostly upregulated in various cancers, while it is also downregulated in four tumor types." (PMID 33266490, 2020). "In the “N-A-C” sequence, WARS1 exhibited a significant upregulation in both blood and tissues, demonstrating a positive correlation with augmented infiltration of immune cells, activation of stromal and immune responses, as well as heightened activity during the cancer immune cycle." (PMID 41145546, 2025). "Beyond this, accumulating evidence has revealed non-canonical functions of WARS1 in immune regulation and angiogenesis, and dysregulated expression has been reported in several cancers, including colorectal cancer." (PMID 41145546, 2025). "There are a few aaRSs that are downregulated in multiple cancer types, including HARS2 (n = 6), WARS1 (n = 4), CARS2 (n = 4), IARS1 (n = 3), RARS2 (n = 3), VARS2 (n = 3), and AIMP3/EEF1E1 (n = 3), suggesting these aaRSs may possess certain specific cancer-inhibiting roles." (PMID 33266490, 2020).
tumor (15 papers, 2020 to 2025). "In established CRC, however, WARS1 expression declined from stage I to IV and correlated positively with stromal and immune scores while inversely with tumor purity, highlighting its link to microenvironmental remodeling." (PMID 41145546, 2025).
infection (11 papers, 2008 to 2024). The state of being infected such as from the introduction of a foreign agent such as serum, vaccine, antigenic substance or organism. "Interestingly, when there is a pathogenic infection, WARS1 is promptly released from monocytes into the extracellular space." (PMID 38177528, 2024). "We recently found human WARS1 to be an endogenous TLR ligand for monocyte/macrophage activation against infection." (PMID 32899943, 2020). "Quite the contrary, many clones targeting genes required for translation, including those encoding aminoacyl-tRNA synthetases (hars-1, lars-1, rars-1, tars-1, wars-1) and eIF subunits, were required for expression of nlp-29 after infection." (PMID 27129311, 2016). "First, WARS1 acts rapidly; it is promptly secreted within several minutes, following infection, without de novo synthesis." (PMID 32899943, 2020). "Beyond its classical role, a non-canonical function of mammalian WARS1 is innate immune activation upon infection." (PMID 32899943, 2020). "During evolutionary process, WARS1 seems to have been optimized, and designed to efficiently perform immunological function, including rapid, nonspecific, and immense responses during acute phase of infection." (PMID 32899943, 2020).
WARS1 also shares sentences with these, for which no sentence is quoted: melanoma (3 papers); Alzheimer disease (2); breast carcinoma (2); distal hereditary motor neuropathy (2); osteosarcoma (2); adenoma (1); amyotrophic lateral sclerosis (1); autoimmune disease (1); cataract (1); cervical squamous cell carcinoma (1); cholangiocarcinoma (1); cocaine addicts (1); colon adenocarcinoma (1); dengue (1); dermatitis (1); diabetes (1); diabetic retinopathy (1); endocervical adenocarcinoma (1); esophageal carcinoma (1); gastric cancer (1); gestational diabetes mellitus (1); glioblastoma (1); kidney failure (1); lymph node metastasis (1); malaria (1); microcephaly (1); multiple sclerosis (1); neurodegenerative disease (1); neurodevelopmental disorder (1); oral cancer (1).
A further 14 diseases each share a sentence with WARS1 in 1 paper.